UGCG (UDP-glucose ceramide glucosyltransferase)
Diseases named in the same sentence as UGCG in open-access papers (continued):
Sharing a sentence is not in itself a finding about the gene and the disease.
heart hypertrophy (3 papers, 2022 to 2024). "To investigate UGCG’s potential contribution to pathological heart hypertrophy, we developed adeno-associated viruses that inhibited UGCG expression." (PMID 37658291, 2023). "Overall, these findings suggest that UGCG inhibition alleviated the pathogenic alterations associated with heart hypertrophy." (PMID 37658291, 2023). "Therefore, this study aims to elucidate the mechanisms underlying the role of UGCG in pathological myocardial hypertrophy and investigate the potential joint mediation of UGCG and B4GalT5 in the regulation of cardiac hypertrophy." (PMID 37658291, 2023). "Importantly, the inhibition of UGCG ameliorated the pathological changes associated with heart hypertrophy, and blocking B4GalT5 attenuated the hypertrophic effects of UGCG." (PMID 37658291, 2023). "Notably, recent studies have linked UGCG to oxidative phosphorylation and cell energy metabolism, further emphasizing the need to consider UGCG’s role in myocardial hypertrophy." (PMID 37658291, 2023). "Conversely, the overexpression of UGCG exacerbated heart hypertrophy following transverse aortic constriction (TAC) modeling." (PMID 39456198, 2024). "Previous studies have also hinted at UGCG’s potential contribution to pathological heart hypertrophy." (PMID 37658291, 2023). "Currently, studies on the role of the UGCG–B4GalT5 axis in pathological heart hypertrophy are limited." (PMID 37658291, 2023). "In our current study, we demonstrated that UGCG and B4GalT5 were remarkably upregulated in heart hypertrophy brought on by pressure overload in vivo or PE in vitro." (PMID 37658291, 2023). "Our findings revealed a collaborative relationship between the two molecules, with B4GalT5 acting as a mediator for UGCG to promote myocardial hypertrophy, adding complexity to their biological roles." (PMID 37658291, 2023). "Taken together, these results suggested that UGCG promotes pathological heart hypertrophy while the inhibition of UGCG attenuates the progression of heart hypertrophy." (PMID 37658291, 2023). "To further unravel the role of UGCG in pathologic heart hypertrophy, we overexpressed UGCG in mouse hearts and observed the pathologic remodeling of hearts after TAC modeling." (PMID 37658291, 2023). "Our findings support the involvement of UGCG in pathological myocardium hypertrophy, wherein UGCG inhibition reduced the development of myocardial hypertrophy and UGCG overexpression accelerated this condition." (PMID 37658291, 2023). "Considering the close association among ERK signaling, ROS levels, and myocardial hypertrophy, and the existence of potential links between ERK signaling, UGCG, and B4GalT5, we examined the expression of ERK and P38-related molecules." (PMID 37658291, 2023). "The overexpression of UGCG in the heart exacerbates cardiac hypertrophy, as evidence by an increase in the cross-sectional area of cardiomyocytes and rate of fibrosis." (PMID 37658291, 2023). "Overall, this study highlights the potential of UGCG as a modulator of heart hypertrophy, rendering it a potential target for combating heart hypertrophy." (PMID 37658291, 2023). "The downregulation of UGCG ameliorated heart hypertrophy, as evidenced by reduced ventricular wall hypertrophy, lower heart weight-to-body weight ratios, decreased left ventricular weight-to-body weight ratios, reduced heart weight-to-tibial length ratios, and decreased cardiac fibrosis." (PMID 39456198, 2024). "Notably, limiting the expression of B4GalT5 impaired the capacity of UGCG to promote myocardial hypertrophy, suggesting that B4GalT5 acts as an intermediary for UGCG." (PMID 37658291, 2023). "Taken together, these findings strongly suggest that the involvement of UGCG and B4GalT5 in myocardial hypertrophy may be mediated through ERK signaling." (PMID 37658291, 2023).
heart hypertrophy (continued). "Our study indicates that blocking the UGCG–B4GalT5 axis can reduce pathological heart hypertrophy; therefore, these UGCG inhibitors may also be used to treat pressure overload-induced remodeling of the heart." (PMID 37658291, 2023). "Compared with the UGCG overexpressing group, the group that received a simultaneous administration of UGCG overexpression and B4GalT5 inhibition showed improved myocardial hypertrophy and myocardial fibrosis, along with a decreased myocardial size and inhibited expression of ANP and BNP." (PMID 37658291, 2023). "This study demonstrated that the inhibition of UGCG expression could partially improve remodeling of stress-induced heart hypertrophy." (PMID 37658291, 2023). "Therefore, we speculated that UGCG and B4GalT5 formed a complex to regulate mitochondrial ROS levels and thereby modulate myocardial hypertrophy." (PMID 37658291, 2023). "Moreover, downregulating UGCG leads to mitigated ERK activation, accompanied by reduced myocardial hypertrophy and heart remodeling." (PMID 37658291, 2023). "Thus, the UGCG–B4GalT5 axis appears to promote the ERK signaling, and our results also confirm that the activation of the UGCG–B4GalT5 axis is accompanied by the activation of ERK, therefore promoting the progression of myocardial hypertrophy." (PMID 37658291, 2023). "Furthermore, the downregulation of UGCG in cardiomyocytes stimulated with PE led to decreased levels of ANP and BNP, suggesting that UGCG suppression may attenuate heart hypertrophy." (PMID 37658291, 2023). "Consequently, our findings suggest that the UGCG and B4GalT5 molecular axes may control ERK signaling, ultimately influencing myocardial hypertrophy." (PMID 37658291, 2023).
hepatocellular carcinoma (3 papers, 2016 to 2024). A malignant tumor that arises from hepatocytes. "The expression of UGCG in human hepatocellular carcinoma has not been elucidated so far." (PMID 29312601, 2017).
ovarian carcinoma (3 papers, 2014 to 2021). A malignant neoplasm originating from the surface ovarian epithelium. "Survival analysis showed that the high levels of SPHK1, KDSR, SMPD1, GALC, SMPD2, UGCG and DEGS1 were associated with poor prognosis of OS in patients with ovarian cancer, among which DEGS1 was the most significant (P = 3E-04)." (PMID 34488809, 2021). "One branch clustered eight genes (NAGA, B4GALT6, HEXA, GLB1, GBA, GLA, UGCG, HEXB) with generally comparable expression levels among the cell lines, except for the UGCG gene which was expressed at considerably higher levels in both HOSE cell lines compared with the ovarian cancer cell lines." (PMID 25294702, 2014).
pancreatic cancer (3 papers, 2019 to 2023). "To formally assess the role of GSL metabolism in KRAS oncogenesis, we treated multiple KRAS mutant pancreatic cancer cell lines and a non-transformed pancreatic epithelial cell strain with a UGCG inhibitor." (PMID 36709325, 2023).
prostate carcinoma (3 papers, 2012 to 2024). A carcinoma that arises from epithelial cells of the prostate gland. "Next, we evaluated alterations in the lipidome following pharmacological inhibition of UGCG in RM-9 and PC-3M prostate cancer cells." (PMID 32855410, 2020). "Targeting of this onco-metabolic pathway via repurposing of eliglustat, a selective small molecule inhibitor of glucosylceramide synthase (UGCG), elicited anti-cancer effects in vitro and attenuated tumor development in an orthotopic syngeneic RM-9 mouse model of prostate cancer." (PMID 39522029, 2024).
bladder cancer (2 papers, 2017 to 2025). "Thus, targeting UGCG expression represents a promising therapeutic strategy for bladder cancer treatment." (PMID 40252176, 2025).
colitis (2 papers, 2022 to 2024). Inflammation of the colon. "In IBD patients and in a DSS induced colitis mouse model UGCG activity was decreased, and knockdown of UGCG resulted in Treg decrease and CD4 effector cell increase." (PMID 36176439, 2022).
depression (2 papers, 2016 to 2024). "In this study, we investigated the expression of the PD-related genes SNCA, GBA1, and UGCG in human blood cells of MDD patients and matched controls and their association with the severity of depression, anxiety, and PD-related laboratory parameters." (PMID 38542193, 2024). "In summary, our findings reveal a significantly elevated peripheral gene expression of SNCA, GBA1, and UGCG among patients currently experiencing depression which partially normalizes for GBA1 and UGCG in the group of medicated patients and also reflects increased depression severity in subgroups." (PMID 38542193, 2024). "We identified significantly elevated expression levels of all three genes in individuals with depression: SNCA (+27%, p = 0.036), GBA1 (+56%, p = 0.014), and UGCG (+75%, p = 0.0002)." (PMID 38542193, 2024). "Therefore, akin to depression severity scores, we examined the correlation between SNCA, GBA1, and UGCG expressions and anxiety scores." (PMID 38542193, 2024).
diabetic kidney disease (2 papers, 2023 to 2025). Progressive kidney disorder caused by vascular damage to the glomerular capillaries, in patients with diabetes mellitus. "There is evidence suggesting that the expression of UGCG is upregulated in diabetic nephropathy and is associated with the downregulation of kidney-protecting genes." (PMID 41049486, 2025). "Data mining was consistent with differential expression of genes encoding enzymes from the Gb3 metabolic pathway in human diabetic kidney disease, including upregulation of UGCG, the gene encoding the upstream and rate-limiting enzyme glucosyl ceramide synthase." (PMID 37958836, 2023).
ichthyosis (2 papers, 2016 to 2018). Disorders of cornification that are characterized by visible scaling and/or hyperkeratosis of most or all of the skin. "Another skin biomarker is UGCG, which can cause ichthyosis when levels are decreased, however, the BlendE treatment stimulated UGCG in this study." (PMID 30373163, 2018). "Mice deficient of UDP-glucose ceramide glucosyltransferase (UGCG), which glucosylates ceramides in the Golgi apparatus, showed an ichthyosis-like skin phenotype with impaired differentiation of keratinocytes." (PMID 26786937, 2016).
neuroblastoma (2 papers, 2020 to 2023). Neuroblastoma (NB) is the most common solid, extracranial childhood tumor. "Most of our predictions, including the CNR2 inhibitor GW405833, the UGCG inhibitor DL-PDMP, the TSPO antagonist PK11195, and the MAPK8/JNK inhibitor AS601245, downregulated the expression of genes induced during the cell cycle, implicating effects on neuroblastoma cell growth." (PMID 31900415, 2020).
aneurysm (1 paper, 2025). Bulging or ballooning in an area of an artery secondary to arterial wall weakening. "Moreover, elevated UGCG expression levels were noted in the ruptured aneurysm wall, reinforcing its involvement in SAH pathophysiology." (PMID 40500739, 2025).
cervical cancer (1 paper, 2025). A primary or metastatic malignant neoplasm involving the cervix. "In cervical cancer, UGCG expression is upregulated in part by human papillomavirus (HPV) oncoproteins (E7 from HPV-16/18), which disrupt the Rb–E2F axis, promoting uncontrolled proliferation." (PMID 41155172, 2025).
chronic lymphocytic leukemia (1 paper, 2025). "UGCG catalyzes the conversion of pro-apoptotic ceramide to anti-apoptotic glucosylceramide, which mediates chemotherapy resistance in chronic lymphocytic leukemia (CLL)." (PMID 41049486, 2025).
colorectal adenocarcinoma (1 paper, 2021). The most common type of colorectal carcinoma. "UGCG expression data from human colorectal adenocarcinomas suggested a lower expression in tumor as compared to normal colon tissue." (PMID 34638879, 2021).
emphysema (1 paper, 2023). "Studies on emphysema and other related diseases have found that inhibiting UGCG expression can promote apoptosis of human pulmonary microvascular endothelial cells by inhibiting the activation of the mTOR pathway." (PMID 37274734, 2023). "In studies on emphysema, UGCG has been proven to affect the apoptosis of pulmonary microvascular endothelial cells by regulating the mTOR pathway." (PMID 37274734, 2023).
glaucoma (1 paper, 2019). Increased pressure in the eyeball due to obstruction of the outflow of aqueous humor. "We found similar levels of GBA and UGCG and lower GBA2 immunoreactivity in glaucoma compared to controls." (PMID 31022733, 2019).
glioblastoma (1 paper, 2021). The most malignant astrocytic tumor (WHO grade IV). "Amongst the genes down-regulated by miR-34a, we selected five genes (ATM, EGFR, BCL2, MET, UGCG) for validation as they have been shown pre-clinically to play critical roles in cell survival and therapeutic resistance in the context of glioblastoma." (PMID 33765907, 2021). "We confirmed that transfection with miR-34a resulted in a significant decrease in the protein and mRNA levels of ATM, EGFR, Bcl2, c-Met and UGCG in glioblastoma cells." (PMID 33765907, 2021).
heart failure (1 paper, 2021). Inability of the heart to pump blood at an adequate rate to meet tissue metabolic requirements. "In addition, UGCG encodes glucosylceramide synthase and older Ugcg–/– mice developed severe heart failure and left ventricular dilatation and even died prematurely." (PMID 35097000, 2021).
intracranial aneurysms (1 paper, 2025). "Furthermore, RNA-sequencing data demonstrated elevated expression of KCNN4 and UGCG in ruptured intracranial aneurysms compared to unruptured ones." (PMID 40500739, 2025).
liver cancer (1 paper, 2021). An epithelial or non-epithelial malignant neoplasm that arises from the liver. "The second study was also carried out with liver cancer cells and showed sorafenib induced UGCG expression resulting in sorafenib resistance." (PMID 34626204, 2021). "Following UGCG inhibition, no alterations of phosphatidylinositol 3-kinase (PI3K)/protein kinase B (AKT) and rapidly accelerated fibrosarcoma (RAF)/ mitogen-activated protein kinase (MAPK)/extracellular signal-regulated kinase (ERK) signaling could be detected in liver cancer cells." (PMID 34626204, 2021).
lymph node metastasis (1 paper, 2025). "A subsequent investigation of associations demonstrated that UGCG and TNFRSF21 expression levels showed a positive relationship with NAC, whereas the expression of BTG2 and MYB, as well as the lymph node metastasis, were negatively correlated with the efficacy of NAC." (PMID 40332226, 2025). "The chi-square test and Fisher’s exact test indicated that postoperative RCB classification demonstrated a statistically significant correlation with the expression levels of UGCG, BTG2, TNFRSF21, and MYB, as well as lymph node metastasis in BRCA patients prior to NAC." (PMID 40332226, 2025). "Specifically, patients were more likely to achieve a higher RCB classification when they were negative for UGCG and TNFRSF21, but positive for BTG2 and MYB, with no lymph node metastasis." (PMID 40332226, 2025).
metastatic melanoma (1 paper, 2019). A melanoma that has spread from its primary site to another anatomic site. "In metastatic melanoma from the TCGA, the expression of UGCG was significantly higher than that of SGMS1 and SGMS2." (PMID 31114500, 2019). "Finally, the clinical outcome in metastatic melanoma patients exhibiting low (20th percentile, medium (between the 20th and 80th percentile), high (80th percentile) SGMS1, SGMS2, and UGCG expression was analyzed in the TCGA cohort." (PMID 31114500, 2019).
osteoarthritis (1 paper, 2024). A noninflammatory degenerative joint disease occurring chiefly in older persons, characterized by degeneration of the articular cartilage, hypertrophy of bone at the margins and changes in the synovial membrane. "UGCG and ESYT1 were considered as hub LMRGs in the development of osteoarthritis, which were regarded as candidate diagnostic markers." (PMID 38637751, 2024). "After synthesizing three machine learning algorithms, Lasso regression, SVM-RFE, and random forest, four hub genes of osteoarthritis lipid metabolism were further screened: UGCG, ESYT1, PTGS2, and CERK." (PMID 38637751, 2024). "Ultimately, 4 hub genes (UGCG, ESYT1, PTGS2, and CERK) were identified as vital players in osteoarthritis lipid metabolism." (PMID 38637751, 2024). "UGCG and ESYT1, which are hub genes involved in lipid metabolism in osteoarthritis, were identified through the utilization of three machine learning algorithms." (PMID 38637751, 2024).
pneumonia (1 paper, 2025). An acute, acute and chronic, or chronic inflammation focally or diffusely affecting the lung parenchyma, caused by an infection in one or both of the lungs (by bacteria, viruses, fungi, or mycoplasma.). "In the current study, we identified three critical enzymes (ACER3, UGCG, and GBA) and developed a diagnostic and prognostic predictive model for pneumonia-induced sepsis (PIS), termed the “AUG model”." (PMID 40394027, 2025). "ACER3, UGCG, and GBA were significantly elevated in both pneumonia and PIS groups relative to the healthy controls (P < 0.05)." (PMID 40394027, 2025).
Sepsis (1 paper, 2025). Sepsis is defined as life-threatening organ dysfunction caused by a dysregulated host response to infection. "Future studies should investigate the therapeutic modulation of ACER3, UGCG, and GBA to assess their direct impact on sepsis outcomes." (PMID 40394027, 2025).
testicular tumor (1 paper, 2025). "In addition to SPTBN4, 31 other molecules were analyzed, revealing potential testicular tumor markers such as TPI1, HMGN1, UGCG, NCL, SET, and EIF3K." (PMID 40321316, 2025).
Thrombocytopenia (1 paper, 2019). A reduction in the number of circulating thrombocytes. "A previous study showed that glucosylceramide synthase (UGCG) is required for infection by one type of bunyavirus (thrombocytopenia syndrome virus, causing severe fever) but not for another (Rift Valley virus) or for other enveloped viruses tested (VSV and EBOV)." (PMID 30918081, 2019).
Venous malformation (1 paper, 2025). A vascular malformation resulting from a developmental error of venous tissue composed of dysmorphic channels lined by flattened endothelium and exhibiting slow turnover. "A previous study indicated that UGCG may contribute to venous malformation pathogenesis by affecting vascular EC activity." (PMID 40500739, 2025).
viral encephalitis (1 paper, 2023). Encephalitis resulting from viral infection. "Our data suggest that GSLs are involved in SVNI-induced pathology and that UGCG inhibitors have antiviral therapeutic potential against alphavirus-induced viral encephalitis." (PMID 37168733, 2023).